RALGPS2 (Ral GEF with PH domain and SH3 binding motif 2)
Description:
Guanine nucleotide exchange factor for the small GTPase RALA. May be involved in cytoskeletal organization. May also be involved in the stimulation of transcription in a Ras-independent fashion (By similarity).
Synonyms: KIAA0351; FLJ10244; FLJ25604; dJ595C2.1
Tractability: Antibody: UniProt places it where antibodies can reach, with medium confidence; its Gene Ontology location is reachable by antibodies, with medium confidence. PROTAC: ubiquitination databases record sites on it; its protein half-life has been measured.
Gene: Protein-coding gene on chromosome 1 (178,725,165 to 178,921,842, forward strand). Ensembl gene ENSG00000116191.
Subcellular location: Cytoplasm; Cell membrane
Subcellular location (Human Protein Atlas): Cytosol; Nucleoplasm
Gene Ontology:
Molecular function: protein binding; guanyl-nucleotide exchange factor activity
Biological process: regulation of Ral protein signal transduction; small GTPase-mediated signal transduction
Cellular component: plasma membrane; cytoplasm
Genetic constraint (gnomAD): Loss-of-function variants: 24 observed, 53 expected, observed/expected ratio (o/e) 0.45, 90% interval 0.33 to 0.64. The upper end of that interval is the gene's LOEUF score, 0.64, which puts it in group 2 of 6, group 1 being the genes least tolerant of losing a copy. Missense variants: 381 observed, 506.42 expected, observed/expected ratio (o/e) 0.75, 90% interval 0.69 to 0.82. Synonymous variants: 178 observed, 173.45 expected, observed/expected ratio (o/e) 1.03, 90% interval 0.91 to 1.16.
Homologues: Orthologues: chimpanzee RALGPS2 (99% identical), dog RALGPS2 (99% identical), macaque RALGPS2 (99% identical), pig RALGPS2 (99% identical), guinea pig RALGPS2 (98% identical), rabbit RALGPS2 (98% identical), rat Ralgps2 (96% identical), mouse Ralgps2 (91% identical), tropical clawed frog ralgps2 (90% identical), zebrafish ralgps2 (84% identical). Paralogues in human: RALGPS1 (62% identical), RAPGEF2 (22% identical), RASGRP3 (22% identical), RASGRP1 (20% identical), RAPGEF6 (20% identical), SOS1 (19% identical), RGL1 (19% identical), RALGDS (18% identical), RASGRP4 (18% identical), RASGRP2 (18% identical), SOS2 (18% identical), RGL3 (17% identical), and 12 more.
Diseases named in the same sentence as RALGPS2 in open-access papers:
RALGPS2 is named in the same sentence as 13 diseases in open-access papers, as found by Europe PMC text mining. Sharing a sentence is not in itself a finding about the gene and the disease. The quoted sentences say what the papers report.
lung carcinoma (4 papers, 2016 to 2020). "Although RalA and RalGEFs are implicated in tumorigenesis, there are few data for RalGPS2 role in lung cancer." (PMID 32802839, 2020). "In addition, RALGPS2 was identified as a putative driver when reducing the cutoff of q-value to 0.2, and RALGPS2 is involved in cell survival and associated with the cell cycle in lung cancer cells." (PMID 31160636, 2019). "In addition, previous research showed that RalGPS2 may play a role in cytoskeleton reorganization and is responsible for survival and the cell cycle in lung cancer cells." (PMID 30700247, 2019). "Unexpectedly, when silencing RalGEF genes in lung cancer cells none of the Ras-dependant RalGEF stood out but one of the Ras-independent RalGEF did: RALGPS2 silencing produced the strongest inhibition of cell population growth among all six RalGEF in four NSCLC cell lines." (PMID 27149377, 2016).
bladder cancer (2 papers, 2018 to 2021). "Furthermore, we characterized the molecular machinery underlying TNTs formation in bladder cancer and kidney cells and unveiled the crucial role played by RalGPS2, which promotes tunneling nanotubes formation through interaction with Akt and PDK1." (PMID 34944949, 2021). "To further characterize TNTs in the six bladder cancer cell lines under investigation, we analyzed the expression of proteins involved in TNTs generation: namely, RalA GTPase and RalGPS2." (PMID 34944949, 2021). "Previously, we demonstrated that RalGPS2 also plays a role in the formation of tunneling nanotubes (TNTs) in bladder cancer 5637 cells." (PMID 34944949, 2021). "In this study, RalGPS2 emerges as a potential common pharmacological target for the development of TNTs-interfering drugs that can reduce tumor progression, at least in bladder cancer, by blocking supportive intercellular mechanisms within the tumor microenvironment." (PMID 34944949, 2021). "Furthermore, in 2018, our group demonstrated, in 5637 bladder cancer cell lines, the role of RalGPS2 (Ral GEF with PH domain and SH3-binding motif 2), a Ras-independent guanine exchange factor (GEF) for the GTPase RalA, in TNTs formation under low serum condition." (PMID 34944949, 2021). "Accordingly, RalGPS2, an independent GEF for the Ral GTPase, was also shown to promote the TNTs formation through rearrangement of actin cytoskeleton in bladder cancer." (PMID 30305100, 2018). "TNTs observed in 5637 cells are functionally active and involved in mitochondrial trafficking; here, we demonstrated that TNTs in bladder cancer cells are also able to transport molecules important for TNTs development, such as LST1 and RalA, but not RalGPS2." (PMID 34944949, 2021).
breast carcinoma (1 paper, 2021). "Moreover, TET3 knocked-down cells under normoxia exhibited an identical alternative splicing pattern of ESRP1 targets (hMENA, SLK, SCRIB, RALGPS2, SLC37A2, FNIP1, CD44, and ARHGEF1) as the hypoxic breast cancer cells." (PMID 34362878, 2021).
ovarian carcinoma (1 paper, 2020). A malignant neoplasm originating from the surface ovarian epithelium. "In turn, RalGPS2 is a HIF-2α-induced gene directly involved in endothelial cell sprouting (and thus angiogenesis) under hypoxic conditions that upregulate TNT formation in ovarian cancer cells." (PMID 33324545, 2020).
tumor (4 papers, 2017 to 2025). "In conclusion, our findings suggest that in the tumor microenvironment, RalGPS2 orchestrates the assembly of multimolecular complexes that drive the formation of TNTs." (PMID 34944949, 2021). "It is suggested that RALGPS2 functions as an inhibitor of RalA signaling and thereby decreases tumor cell proliferation and induces apoptosis." (PMID 27699500, 2017).
cancer (3 papers, 2016 to 2020). A tumor composed of atypical neoplastic, often pleomorphic cells that invade other tissues. "We found that NOTCH2, KAT6A and RALGPS2 are all potential cancer driver genes, demonstrating that this method can help us to find RNA structure-related cancer driver elements." (PMID 31160636, 2019). "Given the important role of Skp2, p21 and p27 regulation for cancer cell proliferation, survival and invasion, future research on the molecular connection between Skp2 regulation and RalGPS2 is warranted for new avenues of intervention." (PMID 27149377, 2016).
neurological disease (1 paper, 2019). "SFN is located at the center of an interaction network of proteins including HYAL2, NBEA, NBR1, AURKAIP1, RALGPS2, and SLC1A2, some of which have known involvement in brain function and neurological disease." (PMID 31029150, 2019).
RALGPS2 also shares sentences with these, for which no sentence is quoted: breast tumor (1 paper); colorectal cancer (1); lung adenocarcinoma (1); nasopharyngeal carcinoma (1); osteosarcoma (1); prostate carcinoma (1).